GABRA6 (gamma-aminobutyric acid type A receptor subunit alpha6)
Description:
Alpha subunit of the heteropentameric ligand-gated chloride channel gated by gamma-aminobutyric acid (GABA), a major inhibitory neurotransmitter in the brain. GABA-gated chloride channels, also named GABA(A) receptors (GABAAR), consist of five subunits arranged around a central pore and contain GABA active binding site(s) located at the alpha and beta subunit interface(s) (By similarity). When activated by GABA, GABAARs selectively allow the flow of chloride anions across the cell membrane down their electrochemical gradient (By similarity). Alpha-6/GABRA6 subunits are found at both synaptic and extrasynaptic sites. Chloride influx into the postsynaptic neuron following GABAAR opening decreases the neuron ability to generate a new action potential, thereby reducing nerve transmission (By similarity). Extrasynaptic alpha-6-containing receptors contribute to the tonic GABAergic inhibition. Alpha-6 subunits are also present on glutamatergic synapses (By similarity).
Tractability: Small molecule: an approved drug acts on it; a high-quality ligand is known; it belongs to a druggable protein family. Antibody: its Gene Ontology location is reachable by antibodies, with high confidence; UniProt places it where antibodies can reach, with medium confidence; UniProt predicts a signal peptide or a membrane-spanning region. PROTAC: a small molecule that binds it is known.
Target class: Ion channel; GABA-A receptor; Ligand-gated ion channel
Safety:
Unwanted effects reported when the protein is acted on. In parentheses: how it was acted on, where the effect was seen, and who reports it.
ataxia (activation, acute dosing; central nervous system, cardiovascular; source: Lynch et al. (2017))
convulsions (inhibition, acute dosing; central nervous system, cardiovascular; source: Lynch et al. (2017))
decreased anxiety (activation, acute dosing; central nervous system, cardiovascular; source: Lynch et al. (2017))
decreased blood pressure (activation, acute dosing; central nervous system, cardiovascular; source: Lynch et al. (2017))
decreased body temperature (activation, acute dosing; central nervous system, cardiovascular; source: Lynch et al. (2017))
decreased cardiac contractility (activation, acute dosing; central nervous system, cardiovascular; source: Lynch et al. (2017))
decreased convulsions (activation, acute dosing; central nervous system, cardiovascular; source: Lynch et al. (2017))
decreased locomotor activity (activation, acute dosing; central nervous system, cardiovascular; source: Lynch et al. (2017))
decreased memory (activation, acute dosing; central nervous system, cardiovascular; source: Lynch et al. (2017))
decreased pain (activation, acute dosing; central nervous system, cardiovascular; source: Lynch et al. (2017))
decreased sleep (inhibition, acute dosing; central nervous system, cardiovascular; source: Lynch et al. (2017))
drug abuse/dependence (activation, acute dosing; central nervous system, cardiovascular; source: Lynch et al. (2017))
increased cardiac output (activation, acute dosing; central nervous system, cardiovascular; source: Lynch et al. (2017))
increased eating (activation, acute dosing; central nervous system, cardiovascular; source: Lynch et al. (2017))
increased respiratory rate (activation, acute dosing; central nervous system, cardiovascular; source: Lynch et al. (2017))
increased sleep (activation, acute dosing; central nervous system, cardiovascular; source: Lynch et al. (2017))
muscle relaxation (activation, acute dosing; central nervous system, cardiovascular; source: Lynch et al. (2017))
Occurrence, Epileptic seizure (brain; source: AOP-Wiki)
Gene: Protein-coding gene on chromosome 5 (161,547,063 to 161,702,593, forward strand). Ensembl gene ENSG00000145863.
Subcellular location: Postsynaptic cell membrane; Cell membrane
Pathways (Reactome):
Neuronal System: GABA receptor activation
Gene Ontology:
Molecular function: benzodiazepine receptor activity; GABA-A receptor activity; extracellular ligand-gated monoatomic ion channel activity; monoatomic ion channel activity; signaling receptor activity; transmembrane signaling receptor activity; transmitter-gated monoatomic ion channel activity involved in regulation of postsynaptic membrane potential
Biological process: chloride transmembrane transport; extrasynaptic signaling via GABA; gamma-aminobutyric acid signaling pathway; inhibitory synapse assembly; signal transduction; synaptic transmission, GABAergic; chloride transport; monoatomic ion transmembrane transport; monoatomic ion transport; regulation of postsynaptic membrane potential
Cellular component: dendrite membrane; GABA-A receptor complex; plasma membrane; postsynapse; postsynaptic membrane; postsynaptic specialization membrane; cerebellar Golgi cell to granule cell synapse; membrane
Genetic constraint (gnomAD): Loss-of-function variants: 44 observed, 47.79 expected, observed/expected ratio (o/e) 0.92, 90% interval 0.72 to 1.18. The upper end of that interval is the gene's LOEUF score, 1.18, which puts it in group 5 of 6, group 1 being the genes least tolerant of losing a copy. Missense variants: 577 observed, 574.57 expected, observed/expected ratio (o/e) 1, 90% interval 0.94 to 1.08. Synonymous variants: 218 observed, 204.15 expected, observed/expected ratio (o/e) 1.07, 90% interval 0.95 to 1.2.
Homologues: Orthologues: chimpanzee GABRA6 (99% identical), macaque GABRA6 (98% identical), pig GABRA6 (94% identical), rabbit GABRA6 (94% identical), guinea pig GABRA6 (93% identical), mouse Gabra6 (91% identical), rat Gabra6 (91% identical), dog GABRA6 (80% identical), tropical clawed frog gabra6 (73% identical), zebrafish gabra6b (71% identical), zebrafish gabra6a (58% identical). Paralogues in human: GABRA4 (71% identical), GABRA1 (58% identical), GABRA3 (58% identical), GABRA2 (57% identical), GABRA5 (56% identical), GABRG1 (46% identical), GABRG2 (44% identical), GABRG3 (43% identical), GABRE (36% identical), GLRA2 (35% identical), GLRA3 (35% identical), GLRA1 (34% identical), and 33 more.